TREM2 (triggering receptor expressed on myeloid cells 2)
Diseases named in the same sentence as TREM2 in open-access papers (continued):
Sharing a sentence is not in itself a finding about the gene and the disease.
Brain atrophy (18 papers, 2015 to 2025). Partial or complete wasting (loss) of brain tissue that was once present. "Conversely, in the PS19 model, which expresses the human tau T34 isoform (one N-terminal insert and four microtubule binding repeats, 1N4R) with the P301S mutation, complete TREM2 knockout reduces brain atrophy associated with tau pathology." (PMID 40247363, 2025). "Supporting this, studies have shown that complete TREM2 loss mitigates tau pathology and brain atrophy in the PS19 model." (PMID 40247363, 2025). "However, heterozygous TREM2 deficiency shows the opposite effect, intensifying tau pathology, brain atrophy, and pro-inflammatory responses in the same model." (PMID 40247363, 2025). "The exacerbated brain atrophy is further accompanied by increased tau hyperphosphorylation in the frontal cortex, indicating a potential mechanistic link between TREM2 dysfunction, ApoE4, and tau pathology." (PMID 40247363, 2025). "The PS19 mice expressing human TREM2 Arg47His (PS19-T2R47H) showed significant attenuation in brain atrophy and lower degree of synapse loss compared to PS19 mice expressing the common variant of human TREM2 (PS19-T2CV)." (PMID 40806186, 2025). "Sayed and colleagues also observed that a complete deficiency in TREM2 protected PS19 mice against tau-mediated microgliosis and brain atrophy." (PMID 37371067, 2023). "TREM2 deficiency or R47H variant of TREM2 in PS19 mice mitigates inflammatory gene expression and protects against brain atrophy at nine months." (PMID 36389767, 2022). "Specifically, under Aβ pathological conditions, TREM2 deficiency significantly promotes tau pathology progression and brain atrophy, potentially because TREM2 is involved in microglial transition from homeostatic to DAM and thus is protective in the context of Aβ pathology." (PMID 41168805, 2025). "In the hTau mouse model, characterized by human MAPT overexpression, TREM2 deficiency accelerates tau phosphorylation and aggregation during early disease progression, although its impact on neurodegeneration and brain atrophy has not been fully assessed." (PMID 40247363, 2025). "Triggering receptor expressed on myeloid cells 2 (TREM2) in cerebrospinal fluid (CSF) is a promising biomarker of microglial activation in vivo, which indicated protective effects on brain atrophy and cognitive performance during early stages of AD and is related to slower amyloid accumulation." (PMID 39238030, 2024). "TREM2 mutation carriers with AD have more extensive brain atrophy than noncarriers with AD." (PMID 25595891, 2015). "Conversely, in another study, total deletion of TREM2 did not affect tau pathology in PS19 mice crossed with Trem2 KO mice; however, brain atrophy and microgliosis were reduced." (PMID 37371067, 2023). "In the P301L Tau model, TREM2 deletion does not show brain atrophy; however, in a double transgenic mouse model where progressive Tau aggregation is driven by mutant Aβ, Trem2 deficiency amplified Tau oligomerization and spreading, culminating in brain atrophy." (PMID 41386298, 2025).
glioblastoma (18 papers, 2016 to 2025). The most malignant astrocytic tumor (WHO grade IV). "Analysing TAM markers in the leading edge of the tumours revealed high CD32a, TREM2 or PD-L1 was associated with poorer overall survival of glioblastoma patients (log-rank test P = 0.020, 0.028, 0.034, respectively, for the top quartile versus lower quartiles of each marker)." (PMID 37324244, 2023). "Conversely, TREM2, which is negatively correlated with immunosuppressive myeloid and T cell exhaustion signatures, plays an immunoprotective role during glioblastoma progression." (PMID 39838454, 2025). "Anti-TREM2 antibody administration during a GL261-induced mouse glioblastoma model also prevents the formation of classical TREM2+ TAM and redirects their transcriptomic signature towards pro-inflammatory states." (PMID 39430099, 2024). "A recent study suggested that TREM2 inhibition remodels macrophages into an immune-active functional status, increases anti-PD-1 efficacy and inhibits tumor growth in a glioblastoma mouse model." (PMID 38515213, 2024). "To show the versatility of our gene-editing platform, we edited the CD14, CD47, TREM2, SIRPA and MERTK genes implicated in the clearance of Aβ and glioblastoma cells." (PMID 37483607, 2023). "First, we show for the first time that TREM2 expression in TAMs correlates with T-cell infiltration and that TREM2 and CD32a expression at the glioblastoma margin predict a poor prognosis." (PMID 37324244, 2023). "Another study showed TREM2/DAP12 expression, not only in microglia, but also in a fraction of neurons in both human and mouse cerebral cortex, and in a glioblastoma cell line; neuronal TREM2 expression was rare in the hippocampus." (PMID 35683020, 2022). "Our study of a larger cohort and different techniques extends these observations by confirming an association between T cells and TAMs at the invading margins of glioblastomas, particularly in the case of anti-inflammatory TREM2+ TAMs, the expression of which correlated with poorer survival." (PMID 37324244, 2023). "Based on the recent developments in TREM2-targeting antibodies, the results of this study may warrant trialling of combination therapy consisting of anti-TREM2 and anti-PD-L1 therapy in glioblastomas expressing these molecules." (PMID 37324244, 2023). "Also, the TREM2-positive mutant demonstrated increased phagocytosis toward both live and apoptotic glioblastoma cells." (PMID 37483607, 2023). "Along similar lines, TGF-β and TREM-2 elevated invasiveness and tumor growth in glioblastoma." (PMID 35159079, 2022). "TREM2 is gaining attention as a potential therapeutic target in various cancers, including glioblastoma (GBM)." (PMID 38203185, 2023). "All cancers expressed TREM2, with the highest levels in glioblastoma multiforme (GBM) and the lowest in LAML." (PMID 33679809, 2021). "CD335 was positively associated with PD-L1 at both the leading edge and infiltrating zone of glioblastomas (P < 0.01) but not in the core; CD335 also positively correlated with CD8+ T cells as well as with CD68/CD163/TREM2 TAMs only at the leading edge (P < 0.01)." (PMID 37324244, 2023).
Insulin resistance (18 papers, 2016 to 2026). Increased resistance towards insulin, that is, diminished effectiveness of insulin in reducing blood glucose levels. "Recently, the close association of TREM2 with insulin resistance and type 2 diabetes, as well as its mechanistic role in MASLD, has attracted considerable attention." (PMID 40438102, 2025). "Published work demonstrated that, down-regulation of TREM2 in adipose tissue in morbid obese patients is associated with advanced insulin resistance, which was in consistent with our experiment." (PMID 31477129, 2019). "To determine the effect of TREM2 deficiency on insulin resistance, we carried out GTT and ITT in both TREM2−/− and WT mice on CFD and HFD." (PMID 31477129, 2019). "Emerging multimodal biomarkers, genetic risk (e.g., APOE4, LRRK2, TREM2), metabolic status (insulin resistance, diabetes), imaging (amyloid/tau PET, MRI), and fluid omics (CSF proteomics, metabolomics), could be integrated into companion-diagnostic frameworks as in oncology." (PMID 41226780, 2025). "Studies in animal models have demonstrated that Trem2−/− mice develop insulin resistance, glucose intolerance, adipocyte hypertrophy, and lipid accumulation under diet-induced obesity conditions." (PMID 40438102, 2025). "Of note, TREM2 deficiency exacerbates WAT hypertrophy and insulin resistance by preventing LAM formation in response to a HFD." (PMID 36982747, 2023). "TREM2 deficient mice showed inhibited recruitment of macrophages to CLS and led to adipocyte hypertrophy as well as insulin resistance." (PMID 36119080, 2022). "In the DioGenes and METSIM studies of overweight or obese participants, SAT expression of components of the TREM2-TYROBP network was found to correlate with clinical measures of insulin resistance." (PMID 34554929, 2021). "Another WA-specific gene, Trem2, was recently shown to enhance adipogenesis, promote glucose and insulin resistance, and diminish energy expenditure." (PMID 27923061, 2016). "However, prior studies have reported that both gain- and loss-of-function of TREM2 lead to increased HFD-induced weight gain, adipocyte hypertrophy, and insulin resistance in mice." (PMID 41509917, 2026). "Whether LAMs can be considered a population that prevents insulin resistance should be determined after analysis in genetically engineered mice, in which LAMs other than TREM2+ LAMs are specifically removed." (PMID 38562458, 2024). "In addition, the knockout of the triggering receptor expressed on myeloid cell 2 (TREM2), which is a great genetic risk factor following APOE4, also exacerbated insulin resistance." (PMID 37623221, 2023). "In addition to M1 and M2 macrophages, other macrophage populations that regulate insulin resistance have been reported recently, including neuropilin-1 (NRP1)+ macrophages and TREM2+ lipid-associated macrophage (LAM)." (PMID 36119080, 2022). "In addition to microglia and cells of myeloid origin (e.g. monocytes, macrophages and osteoclasts), Trem2 is also expressed in mature adipocytes, and has been shown to affect insulin resistance in HFD mice through adipose tissue remodeling." (PMID 33168021, 2020).
depression (17 papers, 2019 to 2025). "Furthermore, the researchers identified several genes associated with depression, such as Cntn1, TREM2, and P2X7, using SNP (single nucleotide polymorphism) and GWAS association analysis." (PMID 38607738, 2024). "Suppression of TREM2 triggers microglial activation and a proinflammatory phenotype, resulting in depression-like behavior." (PMID 38136199, 2023). "The knockout of Nrf2 decreases TREM2 and the microglial arginase 1+ phenotype in the mPFC of Nrf2 KO mice with depression-like behavior." (PMID 36316319, 2022). "We continued to investigate the roles of Nrf2 and TREM2 levels and the microglial arginase 1+ phenotype in the mPFC in the context of depression-like behavior of CSDS mice." (PMID 36316319, 2022). "Apart from an imbalanced protein expression of TREM1 and TREM2 in the hippocampus of depression or AD rat model, results of our previous study have shown a turbulence of TREM1 and TREM2 abundance in T2DM patients." (PMID 36619542, 2022). "The activation of Nrf2 by SFN increased the microglial arginase 1+ phenotype by initiating TREM2 transcription in the medial prefrontal cortex (mPFC) and thus ameliorated depression-like behavior in CSDS mice." (PMID 36316319, 2022). "The specific knockdown of TREM2 in microglia from the LHb reportedly induces proinflammatory cytokine expression and microglial activation, resulting in depression-like behaviors in mice." (PMID 36316319, 2022). "The activation of Nrf2 by sulforaphane (Nrf2 activator) increases the microglial arginase 1+ phenotype by initiating TREM2 transcription in the medial prefrontal cortex (mPFC) and ameliorates depression-like behavior in CSDS mice." (PMID 36316319, 2022). "The knockout of Nrf2 decreased TREM2 and arginase 1+ microglial phenotypes in the mPFC of Nrf2 KO mice with depression-like behavior." (PMID 36316319, 2022). "Downregulating TREM2 expression decreases the microglial arginase 1+ phenotype in the mPFC, resulting in depression-like behavior in SFN-treated CSDS mice." (PMID 36316319, 2022). "Moreover, TREM2 KO mice following hypertension and Pb exposure further aggravated inflammatory levels and anxiety–depression-like behavior." (PMID 39853035, 2025). "Interestingly, TREM2 expression in PD-iMGs was negatively correlated with the severity of panic symptoms and comorbid depression." (PMID 36750547, 2023). "Further, the inhibition of Nrf2-induced TREM2 transcription may play a role in the pathophysiology of depression." (PMID 36316319, 2022). "Taken together, the inhibition of Nrf2-induced TREM2 transcription may contribute to CSDS-induced depression-like behaviors, and the activation of Nrf2-induced TREM2 transcription may confer antidepressant-like effects." (PMID 36316319, 2022). "The present study thus suggests that alterations in the interaction between Nrf2 and TREM2 may contribute to the pathogenesis of depression in the CSDS mouse model." (PMID 36316319, 2022). "In addition, the researchers have provided evidence for a previously unknown action of Trem2 in the LHb, related with depression." (PMID 38892480, 2024). "Finally, activation of Nrf2-induced TREM2 transcription may attenuate depression-like behaviors in CSDS mice." (PMID 36316319, 2022). "Notable nodes that appeared over at least two models included C9orf72, TREM2, APP and MAPT with relationships to input nodes of musculoskeletal and joint disorders, deafness and depression." (PMID 38383858, 2024). "In the present study, the LPS-challenged rats presented not only depression-like behaviors and impairment of learning and memory, but also the decreased expression of TREM1 and increased expression of TREM2 in the hippocampus and PFC." (PMID 32009956, 2019). "The dates indicated that the lack of TREM2 exacerbated anxiety and depression-like behaviors in the hypertensive mice after Pb exposure." (PMID 39853035, 2025).
depression (continued). "Therefore, a decrease in the expression level of hsa-miR-185-5p in AD patients was enhanced by depression and reduced by education, thereby promoting its target CELF2, which reduced the TREM2 function in the microglia and further increased Aβ accumulation." (PMID 36040555, 2022). "However, insight into the expression and biological functions of TREM2 in the context of major depressive disorder (MDD) remains lacking." (PMID 36316319, 2022). "However, the role of TREM2 in the pathogenesis of depression had not been comprehensively assessed." (PMID 36316319, 2022).
diabetes (17 papers, 2019 to 2025). "As an exemplar of use as a non-invasive diagnostic, logistic regression establishes a composite model comprising four proteins (ADAMTSL2, AKR1B10, CFHR4 and TREM2), body mass index and type 2 diabetes mellitus status, to identify at-risk steatohepatitis." (PMID 37037945, 2023). "Further research remains necessary to elucidate the biological relevance of LCN2-linked TREM2 in diabetes." (PMID 35884685, 2022). "This leads to the hypothesis that TREM2 may be a potential target for the treatment of diabetes-associated inflammation by establishing a connection between LCN2-mediated neuroinflammation and microglial activation." (PMID 35884685, 2022). "Furthermore, we suggest that the potential molecular mechanisms underlying the anti- and pro-inflammatory effects of TREM2 in diabetes may require further study." (PMID 35884685, 2022). "Therefore, we investigated whether TREM2 is involved in the pathogenesis of diabetes-associated cognitive decline to provide a new target for the treatment of diabetes-associated neuroinflammation." (PMID 34356130, 2021). "Although type 2 diabetes is a risk factor for dementia, only a limited number of studies have ever addressed the pathophysiological significance of TREM2 in diabetes in both animal models and humans." (PMID 35592778, 2022). "Alternatively, diabetes-related endothelial dysfunction might involve distinct mechanisms that are less dependent on TREM2-mediated inflammation." (PMID 40142624, 2025). "Remarkably, the ectodomain of TREM2, derived from protease-mediated shedding, could be an indirect marker of microglial phenotype that crosses the diabetes-induced leaky BBB." (PMID 36869375, 2023). "Another study demonstrated that TREM-2 suppresses inflammatory responses by negatively regulating the p38 MAPK signaling pathway, alleviating neuroinflammation and cognitive impairment caused by the combined effects of diabetes mellitus (DM) and chronic cerebral hypoperfusion (CCH) on the organism." (PMID 40242752, 2025). "Because the molecular function of TREM2 in regulating microglia-mediated diabetes neuroinflammation remains unclear, elucidating the molecular pathway of TREM2 in hyperglycemia-induced inflammation response is critical for the prevention and treatment of diabetes neuroinflammation." (PMID 34356130, 2021). "The present study demonstrated that TREM2 modulates high glucose-induced microglial inflammation via the NLRP3 signaling pathway providing evidence for the study of chronic neuroinflammation and the immunometabolic response in diabetes neuroinflammation." (PMID 34356130, 2021). "Overexpression of TREM2 in the hippocampus, mediated by adeno-associated virus (AAV)-mediated gene delivery, partially restored these structures and significantly improved diabetes-associated cognitive dysfunction without affecting body weight or glucose homeostasis in the mice." (PMID 40242752, 2025).
gastric cancer (15 papers, 2019 to 2025). A primary or metastatic malignant neoplasm involving the stomach. "Similarly, TREM2 expression was previously reported as associated with shorter survival time in patients with gastric cancer." (PMID 33679809, 2021). "In addition, high TREM2 expression was inversely associated with unfavorable prognosis in gastric cancer and, therefore, could be a useful prognostic biomarker." (PMID 33323544, 2020). "The expression level of TREM2 is significantly upregulated in tumor tissues of patients with gastric cancer (GC), oral squamous cell carcinoma (OSCC), lung cancer, papillary thyroid carcinoma (PTC), renal cell carcinoma (RCC), and prostate cancer (PRAD)." (PMID 38725629, 2024). "According to a report, the up‐regulation of TREM2 is positively related to poor prognosis in patients with gastric cancer." (PMID 33015999, 2020). "This suggests that TREM2 could serve as a potential biomarker for assessing poor prognosis in patients with gastric cancer." (PMID 40242752, 2025). "Nonetheless, the oncogenic roles and potential molecular mechanisms of TREM2 in gastric cancer remain unknown and need in-depth research." (PMID 32647495, 2020). "Also, the expression of TREM2 in gastric cancer is closely related to the prognosis of patients." (PMID 36338707, 2022). "As a negative immune regulator, the expression level of the triggering receptor expressed on myeloid cells-2 (TREM2) was found inversely correlated with patient prognosis in gastric cancer." (PMID 36267973, 2022). "We found similarly reduced level of TREM2 in tumor compared with that in non-tumor tissues in gastric cancer, while there was increased expression in tumor tissues of pancreatic cancer." (PMID 30683932, 2019). "TREM2 were significantly expressed in THP-1 induced TAMs rather than gastric cancer cells lines." (PMID 41253786, 2025). "Intersection genes TREM2, CTHRC1, BGN, NOX4, GPX3, HEYL, and SFRP4 from the GSE72305 and GSE103236 datasets, which were differentially expressed in the normal gastric mucosa than in gastric cancer cells and in lymph node free to lymph node metastatic GC." (PMID 33976737, 2021).